IL6 (interleukin 6)
Diseases named in the same sentence as IL6 in open-access papers (continued):
Sharing a sentence is not in itself a finding about the gene and the disease.
tumor (continued). "Interestingly, ferritin, but not CRP and IL-6, was significantly (P <.05) but modestly (Spearman r < -0.3) associated with lower CAR T-cell expansion normalized to baseline tumor burden at days 7, 14, and 21 post infusion." (PMID 37153543, 2023). "Cells within the TME including macrophages, tumor cells, and mesothelial cells recruit peritoneal endothelial cells to the vicinity of peritoneal metastases and form tubular structures by secreting chemokines, TGF-β, and IL-6 to provide nutrients for OC progression." (PMID 36698173, 2023). "Interestingly, all data highlighted a significant positive correlation between the severity of egg infection and increased IL-1, IL-6, and TNF-α levels, indicating the possible influence of S. haematobium egg antigen on tumor-promoting cytokine levels and supporting BCa development and progression." (PMID 37068081, 2023). "Through a non-canonical NF-κB activation, this could cause IL6 expression to increase and then to up-regulate the STAT3-dependent signaling, ultimately leading to cancer cell survival and silencing of tumor-related inflammatory response." (PMID 37120444, 2023). "Similarly, a specific polysaccharide-peptidoglycan complex (PSPG) derived from specific Lactobacillus casei Shirota, but not other strains, was also proclaimed to limit tumor growth via inhibiting the activation of the IL-6/STAT3 signaling pathway." (PMID 37773196, 2023). "In patients with benign liver disease or non-HCC tumours, serum IL-6 levels are not elevated." (PMID 36901717, 2023). "Inhibition of Notch signaling not only promoted the cytotoxicity of tumor-infiltrating CD8+ T cells, but also enhanced CD8+ T cells’ production of proinflammatory cytokines [including IFN-γ, tumor necrosis factor alpha-like (TNF-α), interleukin-1 beta (IL-1β), IL-6, and IL-8] in those patients." (PMID 37131214, 2023). "However, K1836 treatment inhibited critical components of SASP, including IL-6, GROα and MCP-1 production, which could theoretically modify the tumour microenvironment and interactions of tumour cells with the immune system." (PMID 36825563, 2023). "Finally, NRPP inhibited tumour growth and downregulated the levels of TNF‐α, IL‐1β and IL‐6." (PMID 37610095, 2023). "Previous studies reported that pro-inflammatory cytokines, such as IL-1β, IL-6, IL-17, and IL-22, in the blood reduced significantly and were observed in a CRC patient trial with consumption of 6-month probiotics (IL-1 is required for tumor invasiveness and angiogenesis)." (PMID 37200915, 2023). "Interestingly, CAFs promote tumor growth, angiogenesis, immunosuppression, and metastasis via the secretion of growth factors such as VEGF, TGF-β, cytokines and chemokines (IL-6, CXCL12), PDGF, and MMPs." (PMID 37686315, 2023). "For example, when TAMs are cocultured with hepatoma cells, macrophage-derived IL-6 and IL-8 activate JAK kinase, which phosphorylates STAT3 activating STAT3 signaling in tumor cells and promotes the epithelial mesenchymal transition(EMT), thus enhancing tumor invasion and metastasis." (PMID 36816959, 2023). "Although IL‐6 is incapable of directly inducing the activation and cytokine production of CD8+ T cells, CD8+ T cells were not efficiently primed and activated the anti‐tumor function because of the insufficient helper activity of IL‐6‐sensitized CD4+ T cells, resulting in tumor development." (PMID 37031459, 2023).
tumor (continued). "Following in vivo interaction of CAR T- and tumor cells, CAR T-cells liberate inflammatory cytokines (e.g., TNF-α and IFN-γ), leading to the hyperactivation of macrophages and the secretion of large amounts of IL-6 and IL-1β, which can be effectively abolished by the use of corticosteroids." (PMID 36830750, 2023). "We propose that, at the primary location, OC cells can release specific cytokines (i.e., IL-6, IL-8, IL-1β, G-CSF, GROα, MCP-1, and TNFα) to the tumor environment (i.e., peritoneal fluid) which may attract neutrophils to pro-metastatic niches (for instance, omentum) to induce NETosis." (PMID 36983067, 2023). "In fact, IL-6 preferentially induced STAT3 phosphorylation across all C-GBM immune subsets, while STAT5 was favored in NC-GBM subsets, highlighting that inflammatory stimuli may have different immunomodulatory effects depending on tumor proximity to the LV." (PMID 37192001, 2023). "It has been reported that elevated MDSCs could contribute to tumor progression by remodeling TME through autocrine and paracrine, and a number of soluble factors secreted by MDSCs, such as IL-6, IL-23, HGF, and VEGF, in various tumors including CRC were associated with poor chemotherapeutic effect." (PMID 37781363, 2023). "Collectively, these results suggest that PZP-epithelial cell interaction in the breast could impact the levels of select chemokines/cytokines in the breast environment (IL-6 and TAGLN, for example) with consequential effects on the normal and/or tumor immune environment." (PMID 37709737, 2023). "We find that high expression and T404 phosphorylation of STAT2 inhibit STING subcellular translocation and reduce the production of IRF3-dependent cytokines, including IFNs and T cell chemotaxis, without inhibiting IL-6 production, thus promoting tumor cell survival." (PMID 37036972, 2023). "Our findings suggest that IL6 may represent an important mechanism through which FAK regulates PDAC development and response to therapy, potentially contributing toward the enhanced anti-tumour activity of FAK inhibitors in combination with immunotherapies." (PMID 36138073, 2022). "To achieve this objective, we investigated whether AIF-1 expression in tumor tissue samples from patients with NSCLC was associated with CD68 expression (a marker of monocytes such as macrophages), IL-6 expression, VEGF expression and clinicopathological features of aggressive tumor behavior." (PMID 36520870, 2022). "Many cytokines secreted by tumor cells can recruit macrophages to the TME, but some of them are exclusively produced by CSCs: CCL2, CCL3, CCL5, CXC motif chemokine ligand 12 (CXCL12), olfactomedin-like 3 (OLFML3), stromal-cell-derived factor-1b (Sdf1b), IL-6, IL-33, and CSF-1." (PMID 35740975, 2022). "The proinflammatory cytokines, IFN-γ, IL-4, IL-6 and IL-1β, promote MDSC expansion and activation and generate reactive oxygen species (ROS) and nitric oxide (NO), which contribute to immunosuppression and reduced T cell function within the tumor microenvironment." (PMID 35655772, 2022). "Therefore, CDK inhibitors successfully reduced the expressions of pSTAT3 and transcriptional target genes such as cyclin B1 and IL-6, leading to apoptosis of lung squamous cell carcinoma (LUSC) cells and inhibition of tumor growth in patient-derived xenograft (PDX) models." (PMID 36559280, 2022). "Santiago’s team showed that GZMA can be involved in tumor development and is a potential prognostic target for various cancers; this may be due to the ability of extracellular GZMA to promote the production of NF-κB-dependent IL6 in macrophages." (PMID 36591509, 2022). "Concerning the role of pro-inflammatory cytokines (IL-6, IL-8, and TNF-α), there is evidence that these proteins are produced in a dysregulated manner in oropharyngeal SCC and that they have roles in growth, invasion, the interruption of tumor suppression, immune status, and even survival." (PMID 34251535, 2022).
tumor (continued). "Also in our study, a number of suppressive factors were identified that could be produced by UM cells (e.g., IL-6, galectin 3) and that may explain why we obtained the highest TIL expansion by separating T cells from their tumor environment." (PMID 36249685, 2022). "In this study, we found that the pyroptosis genes including GSDMB, GSDME, NLRC4, NLRP2 and GZMA were hazardous genes in AML, and the genes of proinflammatory cytokines such as IL6 and TNF were found to be protective genes which maybe related with tumor microenvironment." (PMID 36553549, 2022). "To further study whether the exosomes released by IL-6 pretreated MHCC-97L cells (97L-IL6-exo) contain certain molecules that can inhibit the invasion and metastasis of tumor cells, we added the extracted exosomes into the HCC cell line (HCCLM3) with high-metastatic potential." (PMID 35432524, 2022). "In tumor cells, over-activated STAT3 decreases the expression of immunostimulatory factors, including pro-inflammatory cytokines (IL-12, TNF-α), IFN and chemokines (CCL5, CXCL10), while increasing the expression of certain cytokines (IL-6, TGF-β, and VEGF), thus playing an immunosuppressive effect." (PMID 36313280, 2022). "In addition, IL-6 and IL-8 released by fibroblasts could stimulate the upregulation of S100A8 in tumor-infiltrating myeloid cells, and fibroblasts could promote the differentiation of cells in bone marrow into S100A8-expressed TAMs in TME." (PMID 35017463, 2022). "IL-6 can increase the tumorigenic activity of CSCs by enhancing MFG-E8-induced activity, and the combined blockade of IL-6 and MFG-E8 can significantly reduce the number of primary tumor-derived CSCs, whereas blockade of IL-6 alone or MFG-E8 has only a partial antitumor effect." (PMID 35740975, 2022). "Therefore, even without tumor cells arriving, Lin28B enables the pre-metastatic niche to produce IL-6 and IL-10, which is enough to induce N2 conversion." (PMID 35173168, 2022). "Interestingly, studies have also revealed that the activation of Notch signaling could enhance the production of IL-6 in stromal cells in the TME and then promote tumor cell growth and disease progression." (PMID 36466926, 2022). "Thus, neutrophil-mediated IL-6 trans-signaling is unlikely to “restore” IL-6 responsiveness to HER2neg/IL-6Rlow SUM149-like tumor cells." (PMID 35565421, 2022). "Recent studies have demonstrated that M2-like TAM-derived factors, such as interleukin (IL)-6, IL-10, and milk fat globule-epidermal growth factor VIII (MFG-E8), can suppress naïve T cell proliferation, promote carboplatin resistance, and enhance tumor growth." (PMID 36303162, 2022). "These peptides were able to increase the survival time of TC-1 tumor-bearing mice after therapeutic vaccination with an HPV16E7 peptide-based vaccine containing IL-10 inhibitor via increased recruitment of T cells to the tumor site, probably by TC-1-promoted secretion of proinflammatory IL-6." (PMID 35445137, 2022). "MDSC is mainly regulated by factors secreted by tumor cells, such as stem cell factor(SCF) and vascular endothelial growth factor(VEGF) which increase the number of MDSCs and inflammatory cytokines and chemokines such as IL-4, IL-6, IFN-γ, and IL-1β which suppress MDSC." (PMID 36237303, 2022). "However, some research has not detected the elevated expression of IL-6 accompanied by the over-expression of LIF secreted by the tumor in animal models." (PMID 35740622, 2022). "IL-6 also promotes the angiogenesis and metastasis that contribute to the expression of matrix metalloproteinase 2 (MMP-2), expression of VEGF and bFGF by tumor cells and also favor metastasis events by attracting metastatic cells outside the primary site of the tumor." (PMID 36172343, 2022). "In addition, TNF-α increases the production of pro-inflammatory cytokines, such as IL-1, IL-6, IL-8 and RANTES, which may produce complications in tumor pathology." (PMID 35574296, 2022).
tumor (continued). "TAM can release cytokines, especially IL6, which could bind specific receptors on CRC cell surface, activating JAK2/STAT3 signaling pathway, downregulating tumor suppressor miR-506-3p, and relieve the inhibition of the latter on FOXQ1 that results in enhanced invasion and metastasis of CRC." (PMID 35186730, 2022). "The secretion of IL-6 from MSCs increased the secretion of endothelin-1 (ET-1) in cancer cells, which induced the activation of protein kinase B α (AKT) and ERK in endothelial cells, thereby increasing their ability to recruit and sustain angiogenesis in the tumor." (PMID 35741334, 2022). "Sources of IL-6 do not have to be limited to the tumour microenvironment (TME) but can also be produced by hematopoietic stem and progenitor cells (HPSC), epithelial cells, or muscle tissue, all contributing to the rigorous inter-cellular cross-talk, vital for the advancement of the disease." (PMID 36429126, 2022). "illustrated that in mouse pancreatic tumor cells, apigenin(API: a CK2 inhibitor) could suppress the production of tumor-derived factors (TDF), including GM-CSF、IL-6、IFN-γ and MCP-1 to modulate immune cells development and promote tumor regression through enhancing the SHIP-1 expression." (PMID 36530985, 2022). "Thus, the induction of IL-6 function reversed the protective phenotype of IL-9 knockout mice and restored tumour induction to levels indistinguishable from wild-type mice." (PMID 35793807, 2022). "In addition to the high neutrophil:lymphocyte ratio, the increased expression of cytokines including IL-6, TGF-β and G-CSF and of the chemokines CXCL1-3 in C2 tumours suggests pro-tumourigenic (N2) polarisation of these neutrophils, which is typical of tumours with a high NLR87." (PMID 36207323, 2022). "Under hypoxic states, IL-6 promotes hypoxia-inducible factor 1α (HIF-1α, HIF1A) and signal transducer and activator of transcription-3 (STAT-3) transcription, which stimulates VEGF expression, blood vessel formation, and tumor growth through defective angiogenesis." (PMID 36432658, 2022). "For tumor cells, STAT3 decreases the production of immuno-stimulatory cytokines such as interferon-γ (IFN-γ) and tumor necrosis factor-α (TNF-α), along with elevated expression of immuno-exhausting cytokines (IL-6, IL-10, transforming growth factor-β [TGF-β], and VEGF)." (PMID 36080223, 2022). "results: High levels of proinflammatory cytokines (e.g., IFN‐gamma, IL‐6, TNF‐alpha) were expressed by post‐activation T cells in the presence of host tumor cells, whereas naïve T cells and post‐vaccination T cells did not express high levels of these cytokines in the presence of host tumor cells." (PMID 36222328, 2022). "During hepatocellular carcinogenesis, IL-6 trans-signaling pathway, rather than the IL-6 classic signaling contributes to the development of tumors by enhancing tumor proliferation through STAT3 and β-catenin activation and stimulating endothelial cell proliferation to promote tumor angiogenesis." (PMID 36276076, 2022). "However, the frequency of interferon-γ (IFN-γ)-producing effector T cells infiltrated in tumours of anti-IL-6 treated mice did not vary." (PMID 36077801, 2022). "The metastatic tumor model displayed a greater loss of stress ligands (ULBP1, MICA), downregulation of chemokine expression (MCP-1), and higher production of inhibitory soluble molecules (i.e., TGF-β, IL-6), as compared with a non-metastatic tumor model, more resembling the in vivo scenario." (PMID 35205760, 2022). "CAFs and their secreted soluble factors including cytokines (TGF-B, IL-4, IL-6), chemokines (CCLX and CXCL family members), pro-angiogenesis factors (VEGF, PDGF, and HIF), enzymes (MMPs), and ECM proteins (ectodysplasin-A and collagen type-I) contribute to tumor progression." (PMID 36457492, 2022).
tumor (continued). "Furthermore, NGS analysis revealed that NF-κB/RELA targets including CCL2, CXCL8, EDN1, IL-1β, IL-6, and SERPINE1 were further reduced and several potential tumor suppressors, such as FABP3, FADS2, FDFT1, SEMA6A, and PCK2, were synergistically induced by the Gefitinib-+IKK16 treatment." (PMID 36358633, 2022). "Several studies have demonstrated that interleukin-6 (IL-6), transforming growth factor-β (TGF-β), TNF-α, CCL2, CCL17, CCL22, and other immune-regulatory cytokines have significant changes in TME and are closely related to tumor grade, invasiveness and sorafenib resistance." (PMID 36071839, 2022). "An elevated CRP level may reflect a non-specific inflammatory response to tumor necrosis, which in turn indicates the levels of inflammatory cytokines such as IL-6." (PMID 35965580, 2022). "Furthermore, CAFs produce tumour progression stimulating factors such as TGFβ, VEGF, IL-6, and HGF." (PMID 36140243, 2022). "Intriguingly, decreased gene expression of both pro- (Il-1β and Il-6) and anti-inflammatory (Il-10 and Tgf-β) players, as well as T CD8+ dependent effector function genes such as granzyme (Gzma) and perforin (Prf1) in TME of Opn4KO was found when compared to Opn4WT tumor-bearing mice." (PMID 35562405, 2022). "The increased expression of IL-6 and IL-8 in patients without progesterone receptor expression in tumor G3 usually indicates a poor prognosis, and there is a correlation between IL-8 and neovascularization, which may promote metastatic spread." (PMID 36531035, 2022). "Additionally, serum levels of immunostimulatory cytokines including IFN-β, IL-6, TNF-α and IFN-γ have increased by varying degrees in 4T1 tumor (4-, 6.7-, 6-, and 4-fold) and B16F10 tumor (5-, 6.5-, 4-, and 3.2-fold) bearing mice, validating the successful induction of antitumor immune responses." (PMID 36167857, 2022). "Mechanistically, IL-6 induces the expression of HIF-1α, CCL5, and VEGF via the phosphorylation pathway to facilitate the recruitment, extravasation, and colonization of CCR5+ tumor cells in the niche, which lays the foundation for the smooth progress of the next stage." (PMID 35911705, 2022). "Patients with absent tumor hypoxia response within the first 2 weeks of treatment (Δ[18F]FMISO T/M-ratioweek 0-2 ≥0) exhibited elevated mean IL-6 plasma levels that were more than twice as high as in patients with Δ[18F]FMISO T/M-ratioweek 0-2 <0 (33.9 versus 15.8 pg/mL, p=0.016)." (PMID 34773163, 2022). "Among them IL-1, IL-6, epidermal growth factor (EGF) help tumor cells survive, VEGF and IL-8 promote angiogenesis, M2 macrophages, and MDSCs antagonize inflammatory responses, IL-10, TGF-β, C-C motif chemokine ligand (CCL17) inhibits tumor immune function, and TGF-β and MMP promote tumor metastasis." (PMID 36686745, 2022). "IL-6 signalling was the most significantly upregulated pathway in metastatic vs non-metastatic tumours and therefore could constitute a therapeutic target for future personalised therapy." (PMID 35022523, 2022). "Interleukin IL-6 and IL-8 are confirmed to promote angiogenesis in tumor tissues, and treatment of tumor-bearing mice using EGCG suppressed the expression of IL-6 and IL-8 in a concentration-dependent manner, suggesting that IL-6 and IL-8 might mediate the anti-metastatic activity of EGCG." (PMID 36545470, 2022). "Importantly, TC-1 cells were the exclusive IL-6 source in the model suggesting that the therapeutic efficacy is selective when targeting IL-6 on immune and stromal cells rather than on the tumor cells." (PMID 36405719, 2022). "Notably, GSEA analysis also indicated upregulation of epithelial-mesenchymal transition (EMT), inflammatory response, and interleukin-6 (IL-6)-STAT3 signaling in bulk RNA-seq data, which concurs with the observed invasive tumor phenotypes and proposed iCAF switching in the PKN2KO cohort." (PMID 35081338, 2022).